MBP (myelin basic protein)
Diseases named in the same sentence as MBP in open-access papers (continued):
Sharing a sentence is not in itself a finding about the gene and the disease.
Autoimmunity (31 papers, 2004 to 2025). The occurrence of an immune reaction against the organism's own cells or tissues. "B cells are implicated in autoimmunity reactions against self-antigens like the myelin basic protein (MBP) and other autoantigens released after demyelination and cell death." (PMID 37291666, 2023). "Studies have shown a high sequence identity between the U24 gene in the HHV-6 genome and the myelin basic protein (MBP) increasing the risk of autoimmunity in the CNS." (PMID 36311024, 2022). "On the one hand, microbial molecular mimics of myelin-associated proteins such as the myelin basic protein (MBP) could trigger autoimmunity." (PMID 38845026, 2024). "used a recombinant Vaccinia virus expressing myelin basic protein (MBP) to trigger autoimmunity in Rag2-/- mice expressing an MBP-specific CD8+ TCR." (PMID 38022632, 2023). "In animal models, injection of foreign MBP gives rise to cross-reactivity to native MBP and inflammation, autoimmunity and clinical symptoms similar to human RRMS." (PMID 25885816, 2015). "Our results show that, unlike the previously reported HLA-DR-dependent susceptibility to MBP-, PLP-, or MOG-induced EAE, the pathogenic autoimmunity against PLP, as well as against MOBP, was dependent on HLA-DQB1*0602 rather than HLA-DRB1*1501." (PMID 22316121, 2012). "With this background, this study was conducted to investigate the relationship between serum levels of serotonin and anti-myelin-basic protein (anti-MBP) auto-antibodies, which are possible indicators of autoimmunity to CNS, in a group of autistic children." (PMID 21696608, 2011). "We are the first to investigate the possible role of hyperserotonemia in the induction of autoimmunity, as indicated by serum anti-myelin-basic protein (anti-MBP) auto-antibodies, in autism." (PMID 21696608, 2011). "It was concluded that the JE virus which normally causes inflammation and neuronal degeneration in the CNS induces proliferation of specific T cells which mediate autoimmunity to destroy components of axon-surrounding myelin such as MBP." (PMID 21356046, 2011). "For instance, addition of myelin basic protein to the enveloped virus VV was shown to be important for autoimmunity and induction of encephalomyelitis." (PMID 17949490, 2007). "Proof of concept that virus peptides could induce CNS autoimmunity to was shown by Fujinami and Oldstone in 1985, where rabbits immunised with either MBP or a homologous peptide from Hepatitis B virus (HBV) polymerase developed EAE." (PMID 38022632, 2023). "Furthermore, it is well known that lymphocytes demonstrate autoimmunity against CNS components such as myelin basic protein (MBP) following SCI." (PMID 37175842, 2023). "It has been suggested that under certain circumstances, these MBP-specific T-cells may become activated and induce autoimmunity." (PMID 32218783, 2020). "Moreover, MMP9 can also cleave myelin compounds, such as type II gelatins and myelin basic protein, leading to the generation of epitopes that induce autoimmunity." (PMID 31440381, 2019). "Taken together, our results suggest that autoimmunity may play an important role in the destruction of components, e.g., MBP, of axon-surrounding myelin, resulting in demyelination in the mouse brain after infection with the JE virus." (PMID 21356046, 2011). "Immunity against synthetic peptides of the TCR has been shown to be effective in preventing or reducing the severity of EAE in the rat, suggesting that autoimmunity against the TCR reacting with encephalitogenic sequences of MBP is key to immunoregulatory events." (PMID 15541175, 2004). "Additionally, deficient or ineffective initiation of SCI-induced immune suppression may result in autoimmunity, in which MBP-reactive and memory T cells, B cells, and autoantibodies have been reported to play a role." (PMID 39664385, 2024).
Autoimmunity (continued). "As another and complementary model of CNS autoimmunity, we induced EAE in B10.RIII mice that had been made VAD or VAI, following an optimized immunization regimen with the whole MBP protein." (PMID 40492202, 2025). "The main proteinaceous components of myelin, myelin basic protein (MBP), myelin oligodendrocyte glycoprotein (MOG), and proteolipid protein (PLP), are effective autoantigens and targets of autoimmunity in MS." (PMID 36614334, 2023). "This increased expression was highly co-localized with MBP-positive myelinated axons, the main targets of autoimmunity in EAE, while the colocalization of MANF with MBP was reduced along with MANF-levels during the peak of the disease." (PMID 34305531, 2021). "In the case of MS, peptides from the three major myelin proteins—myelin basic protein (MBP), myelin oligodendrocyte glycoprotein (MOG), and proteolipid protein (PLP)—have been identified to be related to autoimmunity." (PMID 33371329, 2020). "Cleavage of myelin basic protein or type II gelatins by MMP-9 will produce remnant epitopes and contribute to the development of autoimmunity." (PMID 19272186, 2009). "Indeed, the cleavage of myelin basic protein or type II gelatins by MMP-9 will generate remnant epitopes and contribute to develop autoimmunity." (PMID 23555760, 2013). "Because MBP-specific antibodies are also present in some asymptomatic mice, it seems that MBP is probably not the only target which can trigger autoimmunity against myelin." (PMID 21356046, 2011). "In this study, we analyzed public data to identify relationships between proteins or metabolites from microorganisms and the myelin proteins MBP and MOG, since such similarities may represent cases of molecular mimicry that contribute to autoimmunity and MS pathogenesis." (PMID 39775333, 2024). "Common to some viral diseases and autoimmune pathologies, catalytic Abs (Abzymes) hydrolyzing DNA and a variety of proteins were described in HIV/AIDS patients: histones, myelin basic protein (MBP), HIV integrase and HIV reverse transcriptase, β-casein and serum albumin." (PMID 35335016, 2022). "In the case of protection from viral infection, CD4 CTLs may be specific for viral Ag(s), whereas in the case of inducing autoimmunity, such as in colitis or EAE, these cells could be specific for microbiota in the intestine or self Ag(s), such as myelin basic protein." (PMID 28280496, 2017). "As immune responses against myelin autoantigens, including myelin basic protein (MBP) and MOG, may be critical in MS pathogenesis, the formation of the myelin sheath around CNS axons may be an absolute requirement for CNS autoimmunity to occur." (PMID 23705890, 2013).
Cognitive impairment (25 papers, 2012 to 2025). Abnormal cognition is characterized by deficits in thinking, reasoning, or remembering. "Since myelin integrity in the hippocampus is essential for efficient synaptic transmission and neuronal connectivity, the loss of MBP in CPZ-treated animals likely contributed to the cognitive impairment observed." (PMID 41164371, 2025). "BCAS mice exhibited a biphasic reduction of CBF and cognitive impairments, parallel with a significant loss of myelin basic protein (MBP) in white matter tracts." (PMID 41137045, 2025). "Our findings showed significant age-related elevation in C1q localized to myelin basic protein, and this increase is associated with more severe cognitive impairment." (PMID 39399501, 2024). "MA at GV20 and ST36 can increase CBF, protect myelin integrity, reduce the loss of myelin basic protein, and improve cognitive impairment in BCCAO rats." (PMID 37397457, 2023). "In addition, sevoflurane anesthesia during pregnancy caused the expression of MBP decreased and demyelination in mice, leading to cognitive impairment in the offspring." (PMID 34497527, 2021). "MBP protein loss is closely associated with cognitive impairment in animal models." (PMID 30799999, 2019). "Of particular interest, we found that the intervention effect of a zinc supplemented diet on cognitive impairment caused by developmental seizures was consistent with the effect on hippocampal regenerative mossy fiber sprouting and was consistent with expression of MBP." (PMID 31551684, 2019). "Next, we analyzed myelin basic protein (MBP) staining patterns in the cingulate cortex in our mouse model of cisplatin-induced cognitive impairment as a measure of white matter integrity." (PMID 27018597, 2016). "The increase in coherency of myelin basic protein (MBP)+ fibers that we observed in the brains of these cisplatin-treated mice may underlie the impaired white matter integrity detected by neuroimaging in patients treated with platinum-based compounds and reporting cognitive deficits." (PMID 27018597, 2016). "In this study, we were surprised to find that MIF, a specific microglia activation inhibitor, showed different action on cognitive impairment and MBP expression after rUCCAO compared with minocycline treatment." (PMID 26174710, 2015). "Because white matter damage contributes to cognitive impairment following CCH, we examined the damage to the myelin sheath in the corpus callosum by measuring the loss of myelin via Luxol fast blue staining and by assessing the loss of myelin basic protein (MBP)." (PMID 35936778, 2022). "Consistently, we found that the MBP level in the striatum decreased in BCCAO rats, compared with the controls, demonstrating that BCCAO induced myelin loss and sustained to at least 4 weeks, along with cognitive impairment based on the MWM test and novel object recognition test." (PMID 35769369, 2022). "Moreover, correlation analysis between target quadrant time (MWM test) and LFB or MBP staining was performed to determine whether WM integrity was related to cognitive impairment." (PMID 35403823, 2022). "Up-regulation of MBP protein levels in the high zinc diet-treated seizure group (SE + ZS), as well as the corresponding improvement of cognitive impairment and reduced hippocampal mossy fiber regenerative sprouting, may represent a compensatory mechanism for neuronal membrane damage and repair." (PMID 31551684, 2019). "Up-regulation of MBP protein levels in the high zinc diet-treated seizure group as well as the corresponding improvement of cognitive impairment and reduced hippocampal mossy fiber regenerative sprouting, may represent a compensatory mechanism for neuronal membrane damage and repair." (PMID 31551684, 2019).
Cognitive impairment (continued). "However, we were interested to find that MIF cannot duplicate the effect of minocycline on MBP expression and even aggravated cognitive impairment in object recognition test and Morris water maze test (two-way ANOVA indicated a significant difference, P < 0.001) at 32 d after hypoperfusion." (PMID 26174710, 2015). "Behavioral tests confirmed cognitive deficits correlated with myelin damage, supported by TEM, LFB staining, and MBP analyses, which revealed significant demyelination affecting neural conduction." (PMID 40332557, 2025).
Alzheimer disease (19 papers, 2012 to 2026). A progressive, neurodegenerative disease characterized by loss of function and death of nerve cells in several areas of the brain leading to loss of cognitive function such as memory and language. "Thus, the increase of MBP may one of the reasons why aging increases susceptibility to Alzheimer’s disease." (PMID 37875604, 2023). "Specifically, citrullinated GFAP is a characteristic feature in MS and Alzheimer’s disease, and MBP, a major component of myelin sheath structure, is profoundly over-citrullinated in MS." (PMID 26441823, 2015). "Also, it has been shown that in Alzheimer’s disease (AD), against the background of neuronal death and myelin sheath destruction, MBP is present within extracellular Aβ plaques." (PMID 41226495, 2025). "Moreover, MBP has also been shown to be differentially methylated in other neurodegenerative diseases with white matter pathology, such as Alzheimer’s disease (AD)." (PMID 37286732, 2023). "Furthermore, deletion of the MBP gene led to a significant reduction in cerebral β-amyloid levels in an Alzheimer’s disease model, Tg-3xFAD mice." (PMID 37875604, 2023). "MBP signal was quantified similarly in striosomes of a mouse model for Alzheimer’s disease, 5X FAD." (PMID 28482862, 2017). "Interestingly, in a transgenic mouse model of Alzheimer’s disease, HSA-treated mice showed increased myelin integrity and myelin basic protein (MBP) protein level." (PMID 38146334, 2023).
demyelination (19 papers, 2011 to 2025). "Overall, our results confirmed the important role of serum anti-PLP and anti-MBP antibodies in post-COVID demyelination." (PMID 41465566, 2025). "FTY720 treatment in rodent demyelination models can dampen symptoms by enhancing myelin repair and upregulate expression levels of MBP, a major component of myelin." (PMID 37438826, 2023). "We and others recently demonstrated that metabolic oligodendrocyte stress, induced by intoxication with the mitochondrial toxin cuprizone, results in myelin basic protein (MBP) citrullination which triggers autoimmune inflammatory demyelination." (PMID 35250482, 2022). "We have tested four different mAbs specific for OMGP for inducing demyelination in combination with T cells specific for MBP or OMGP that breach the blood–brain barrier." (PMID 33256847, 2020). "To assess the extent of cerebellar demyelination, we quantified the percent of MBP-covered NF-H+ axons." (PMID 28340598, 2017). "Both early and late active demyelination lesions are characterized by infiltration of MBP-positive macrophages, indicating release of MBP in demyelinating lesions." (PMID 25255088, 2014). "In this study, we found that EB-induced demyelination lowers the level of MBP in the rat brain." (PMID 36139346, 2022). "In in vitro demyelination models, EGF has also been observed to promote the remyelination and expression of MBP and CNPase and appears to be more efficient for this process than other growth factors such as FGF and PGDF." (PMID 35330085, 2022). "These higher expressions of MAG, MBP, and CDK5 in TG mice increase protecting adaption, thus decrease the sensitivity to METH-induced demyelination." (PMID 29467717, 2018). "Originally developed as a substitute for myelin basic protein (MBP) in inducing paralytic disease in animals, the drug inhibited the induction of EAE and reversed signs of demyelination." (PMID 23805274, 2013). "In the splenium of the CC, regardless of the age group, a reduction of MBP was found in the demyelination group." (PMID 30297998, 2018). "The specific disappearance and reappearance of 21.5 kDa P-MBP occurred in parallel with demyelination and remyelination in cuprizone- and aging-induced demyelination models, while the total MBP levels were not significantly correlated with these processes." (PMID 21799684, 2011). "The double labeling experiments with CC1/MBP and CD4 showed CD4+ cells were abundantly distributed in the white matter upon EAE induction (arrowhead), and were specifically localized to demyelination lesions, while CC1+ OLs were absent from these areas." (PMID 22912731, 2012).
Anxiety (16 papers, 2016 to 2025). Intense feelings of nervousness, tension, or panic often arise in response to interpersonal stresses. "Notably, other studies have reported that MBP dysfunction(s) were associated with physiological response to stress and emotional states, including anxiety and depression in adulthood, all possible indicators for commonalities in brain traumas." (PMID 30283295, 2018). "PBM via NIR irradiation alleviated anxiety and depression symptoms, as well as neuronal cell death, in TgF344-AD mice, and it suppressed neuronal degeneration by increasing the expression of MBP, MAP2, and PSD95, which are nerve fiber and synapse markers." (PMID 37895108, 2023). "Our findings showed that the effects of the MBP on test anxiety were comparable to those of the CRP." (PMID 27764151, 2016). "Another four studies reported large effects of MBP’s on the reduction of FoC or pregnancy related anxiety in different populations of pregnant women." (PMID 27821151, 2016). "For example, Xiao Chai Hu decoction may alleviate patients' anxiety symptoms by decreasing the levels of factors related to brain neurological function such as S100B, MBP, NSE and IGF-1." (PMID 38027586, 2023). "Notably, stress-induced anxiety-like behaviour is positively correlated with hippocampal dentate gyrus oligodendrocytes and myelin basic protein." (PMID 37592237, 2023). "Interestingly, greater oligodendrocyte cell density and greater MBP intensity specifically in the dentate gyrus of the hippocampus corresponded to greater anxiety-like behavior after stress." (PMID 34903726, 2021). "Given the promising impact of MBP’s on fear and stress, and the promising application for women experiencing pregnancy-related anxiety, in this study we will evaluate the effectiveness of MBCP on FoC in a population of pregnant women with a high level of FoC during the perinatal period." (PMID 27821151, 2016). "Moreover, the mPFC neuronal population was activated using excitatory chemogenetic receptor hM3Dq, which largely replicated exercise effects including elevated MBP expression, higher density of oligodendrocytes and precursor cells, as well as decreased anxiety-like behaviors." (PMID 36658152, 2023). "GH also reduced microglial (Iba-1) and astrocytic (GFAP) hypertrophy, restored MBP and β-III tubulin levels, enhanced Purkinje cell survival, and improved motor coordination and anxiety-like behavior in adulthood." (PMID 41226706, 2025). "The no-training condition showed a decreased test anxiety; however, the effect size of the no-training condition was smaller than those of the MBP and CRP." (PMID 27764151, 2016). "In this context, we speculated that decentering components of the MBP and CRP might contribute to reduce test anxiety." (PMID 27764151, 2016). "Administration of low dose LPS 1 day after injury was associated with a reduction in neuronal injury, a restoration of levels of myelin basic protein (MBP) and PSD-95 and no behavioral changes in locomotion, anxiety, depressive-like behavior or cognition at 3 months post-injury." (PMID 33679762, 2021).